CEACAM1 (CEA cell adhesion molecule 1)
Diseases named in the same sentence as CEACAM1 in open-access papers (continued):
Sharing a sentence is not in itself a finding about the gene and the disease.
melanoma (continued). "Further, CEACAM1-3S enhanced immunogenicity of melanoma cells by cell surface upregulation of NKG2D receptor ligands, thereby sensitizing them to lysis by natural killer cells." (PMID 30050594, 2018). "In mouse melanoma cell lines, CEACAM1-4L isoform downregulates cell surface levels of NKG2D ligands MICA and ULBP2 while CEACAM1-3S and -3L overexpressions in CRC cell lines cause sequestration of MICA/B intracellularly, preventing it from activating NK cells." (PMID 30406153, 2018). "In melanoma, the role of CEACAM1 is well established, with a significant number of studies unanimously demonstrating its prognostic value in diagnosis, progression, and metastasis." (PMID 30406153, 2018). "After transfection of the human MeWo melanoma cells, puromycin selection and limiting dilutions, the new sublines were analyzed for CEACAM1, 3, 5, 6, 8 and 21 expression by flow cytometry." (PMID 30089785, 2018). "We investigated the functional role of CEACAM1 in a spontaneous metastasis xenograft model of human melanoma in scid mice using BRAF wildtype MeWo cells with and without RNAi mediated knockdown of CEACAM1." (PMID 30089785, 2018). "The majority of CD8+ T cells in human melanoma samples were reported to be CEACAM1+ and CEACAM1 and TIM-3 are co-expressed on exhausted murine T cells during induction of tolerance." (PMID 30349641, 2018). "In the cohort examined in our study a high CEACAM1 expression in melanoma was negatively correlated with survival which corresponds well with the literature, verifying this correlation in an additional cohort of patients." (PMID 30089785, 2018). "CEACAM1 staining in a certain area of an individual melanoma sometimes correlated with IGFBP7 staining intensity in the same area, but more often did not (serial sections)." (PMID 30089785, 2018). "MRG1 blocked CEACAM1 homophilic interactions that inhibit T cell effector function, enhancing the killing of CEACAM1+ melanoma cells by T cells." (PMID 30341336, 2018). "Similar to HCC, expression of CEACAM1 was found at the invasive front of melanomas and showed significant prediction of metastatic disease." (PMID 30314283, 2018). "The essential interplay between CEACAM1 and cells of the immune system is well documented in melanoma." (PMID 30406153, 2018). "It should be noted that CEACAM1 expression has been modulated in vivo using an anti-CEACAM1 antibody (MRG1) to inhibit CEACAM1-positive melanoma xenograft growth in SCID/NOD mice." (PMID 30341336, 2018). "High expression of CEACAM1 in the melanoma samples correlated with high LXN expression (φ = 0.37, p < 0.001) and also CEACAM1 staining in a certain area of an individual melanoma often correlated with LXN staining intensity in the same area (serial sections)." (PMID 30089785, 2018). "A study model investigating aspects of melanoma cell long coincubation with antigen-specific TIL demonstrated that the surviving melanoma cells increase their surface CEACAM1 expression, which in turn confers enhanced resistance against fresh TIL." (PMID 30406153, 2018). "Downregulation of CEACAM1 has been described in prostate, colon, and breast cancer, whereas CEACAM1 upregulation correlates with disease progression in melanoma and pulmonary adenocarcinoma." (PMID 30050594, 2018). "Stable expression of CEACAM1 on melanoma cells enhanced invasion and migration of the cells in vitro Reduced expression of CEACAM1 was reported upon malignant transformation in mice and in samples of human colorectal cancer." (PMID 30349641, 2018). "In malignant melanoma cell lines, CEACAM1-3S, CEACAM1-3L, CEACAM1-4S, and CEACAM1-4L affected migration, invasion, and immunogenicity in an isoform-specific manner." (PMID 30050594, 2018). "Our findings diverge from previously published observations in which CEACAM1 was identified as a marker of exhausted T cells in the tumor microenvironment with majority of the CD8+ T cells in human melanoma samples expressing CEACAM1 by IHC." (PMID 30349641, 2018).
melanoma (continued). "More specifically, CEACAM1 expression correlates with good prognosis in mammary carcinomas, whereas in melanomas, up-regulation of CEACAM1 is accompanied by poor overall survival." (PMID 27572314, 2016). "In activated human tumor-infiltrating lymphocytes derived from patients with melanoma, all cells express CEACAM1, with inhibitory effects following homophilic interaction." (PMID 27642217, 2016). "The effect of manipulations in SOX9 expression on CEACAM1 was tested in several melanoma cell cultures." (PMID 26885752, 2016). "In this study, we examine the role of transcription factor SOX9 in the regulation of CEACAM1 expression and immune resistance in melanoma cells." (PMID 26885752, 2016). "In melanoma, through homophilic interactions, CEACAM1 inhibits natural killer (NK) cell activity and effector functions (such as cytotoxicity and interferon gamma (IFNγ) release) of tumor-infiltrating lymphocytes (TILs)." (PMID 27642217, 2016). "A central factor in this interaction is CEACAM1 (carcinoembryonic antigen cell adhesion molecule 1), a transmembrane glycoprotein previously shown in our lab to protect melanoma cells from T cell-mediated killing." (PMID 26885752, 2016). "Surprisingly, none of the deletions had any impact on the suppressive effect of SOX9 on the CEACAM1 promoter in two different melanoma cell lines." (PMID 26885752, 2016). "As activated lymphocytes also express CEACAM1, its homophilic interactions between them and melanoma cells inhibit TIL mediated killing." (PMID 26885752, 2016). "Since melanoma is an immunogenic disease, CEACAM1 constitutes an attractive target for immunotherapy." (PMID 27642217, 2016). "It is also worth noting that the role of CEACAM1 in colon epithelium is distinctly different than in melanoma." (PMID 26885752, 2016). "Novel specific monoclonal antibodies for melanoma immunotherapy, based on functional blocking of CEACAM1, are now available from cCAM Biotherapeutics (CM24) and Agenus Inc.." (PMID 27642217, 2016). "SOX9 and CEACAM1 mRNA levels were evaluated in 24 melanoma cell cultures to test for a possible correlation." (PMID 26885752, 2016). "In this study we investigate the role of SOX9 in regulating CEACAM1 expression and thereby immune resistance in melanoma cells." (PMID 26885752, 2016). "This correlates with the subsequent up-regulation of CEACAM1 and its known role in protecting melanoma cells from an immune attack." (PMID 26885752, 2016). "We recently developed a novel approach for melanoma immunotherapy, based on a functional blocking of CEACAM1 with a specific mAb." (PMID 26885752, 2016). "The reviewed articles highlighted the important role of CEACAM1 expression in the development of melanoma." (PMID 27642217, 2016). "Accordingly, CEACAM1 was up-regulated in all melanoma lines both at the mRNA and protein levels, except for A375." (PMID 26885752, 2016). "The level of soluble CEACAM1 inversely correlated with time to death from melanoma in patients with active disease." (PMID 27642217, 2016). "CEACAM1 directly inhibits activated NK and T lymphocytes and this results in an increase of its expression in melanoma cells that survive an in vitro immune attack, which can further inhibit new immune cells." (PMID 27642217, 2016). "In melanoma, CEACAM1 promotes tumor aggressiveness, whereas in colon carcinoma it acts as a tumor growth suppressor and is down-regulated in the early phases of tumor development." (PMID 26885752, 2016). "CEACAM1 positive lymphocytes are more abundant in patients with melanoma; melanoma cells possibly transfer CEACAM1 to the attacking lymphocytes, affecting efficient immune reactions." (PMID 27642217, 2016). "Recent studies evidenced the correlation between CEACAM1 expressions in melanoma cell lines and melanoma tissue with microphthalmia-associated transcription factor (MITF)." (PMID 27642217, 2016). "In melanoma patients, the level of CEACAM1 correlates with the amount of tumor cells that secret CEACAM1." (PMID 27642217, 2016).
melanoma (continued). "CEACAM1 promotes melanoma progression: CEACAM1 enhances migration and invasion of melanoma cells; CEACAM1 impairs the antitumor immune responses of NK and T cells." (PMID 27642217, 2016). "Out of the 40 cases of CEACAM1 positive melanomas, 28 had metastasized while out of the 60 cases of CEACAM1 negative melanomas, only 6 had metastasized." (PMID 27642217, 2016). "As CEACAM1 is a pivotal protein in melanoma biology and immune crosstalk, further understanding of its regulation can provide new insights and contribute to the development of novel approaches to therapy." (PMID 26885752, 2016). "In conclusion, we show that SOX9 regulates CEACAM1 expression in melanoma cells, and thereby their immune resistance." (PMID 26885752, 2016). "Antibodies 4D1/C2 against CEACAM1 have a higher specificity and sensitivity for melanoma cells in lymphatic and hematogenous metastases and can be added to the standard panel of antibodies." (PMID 27642217, 2016). "Correlation between serum CEACAM1 and melanoma progression and survival supports CEACAM1 as a standard biomarker in monitoring melanoma patients and assessing the response to immunotherapy." (PMID 27642217, 2016). "TIL14 cells express CEACAM1 at high level, allowing for CEACAM1 homophilic interactions with melanoma cells." (PMID 26885752, 2016). "Results of the experiment showed a progressive increase in CEACAM1 expression on melanoma cells that resisted the attack of infiltrating lymphocytes." (PMID 27642217, 2016). "Median CEACAM1 expression was 1% in benign nevi, 9.6% in dysplastic nevi, 18% in thin superficial spreading melanomas (Breslow tumor thickness < 1 mm), and 74% in thick superficial spreading melanomas (Breslow tumor thickness > 1 mm) (p < 0.0001)." (PMID 27642217, 2016). "Here we focus on the transcription factor SOX9, and show that it influences CEACAM1 expression and immune resistance in melanoma cells." (PMID 26885752, 2016). "Compared with dysplastic nevi, median expression of CEACAM1 was significantly increased in thick superficial spreading melanomas." (PMID 27642217, 2016). "High expression levels of CEACAM1 have been detected in melanoma, adenocarcinomas, and small cell lung cancers while lower levels of CEACAM1 have been detected in colon, prostate, and breast cancers." (PMID 27642217, 2016). "The authors highlighted a significant positive correlation between CEACAM1 expression and Breslow tumor thickness and Clark level of superficial spreading melanomas." (PMID 27642217, 2016). "Upregulation of CEACAM1, induced by IFNγ on melanoma cells that survive TIL-mediated attack, renders these cells even more resistant." (PMID 27642217, 2016). "We have reviewed the literature and have discussed the important role of the expression of the carcinoembryonic antigen cell adhesion molecule 1 (CEACAM1) in the development of melanoma." (PMID 27642217, 2016). "Though additional studies in larger cohorts and various therapeutic scenarios are warranted, they imply on the possible importance of serum CEACAM1 in early detection of melanoma and in prediction of response to immunotherapy." (PMID 26688824, 2015). "In this work we demonstrate that serum CEACAM1 sensitively reflects tumor volume in mice xenografted with human melanoma." (PMID 26688824, 2015). "Altogether, the results presented in this study imply a direct correlation between elevation in serum CEACAM1 levels, disease progression, and response to treatment and strengthen the prognostic value of sCEACAM1 in melanoma." (PMID 26688824, 2015). "The expression of the CEACAM1 adhesion molecule on melanoma cells is a strong predictor of poor prognosis." (PMID 26688824, 2015). "In order to test the potential value of serum CEACAM1 for monitoring disease progression and response to treatment in melanoma patients, a retrospective longitudinal clinical trial was performed." (PMID 26688824, 2015).
melanoma (continued). "Nevertheless, our findings warrant further mechanistic analysis to focus on the molecular crosstalk between CEACAM1 and molecules, known to be involved in the metastatic cascade of melanoma cells." (PMID 26539411, 2015). "Together these data indicate a crucial role of CEACAM1-4L in the initiation of metastatic processes in malignant melanoma." (PMID 26539411, 2015). "We have previously shown that an unusual elevated level of CEACAM1-positive T cells and NK cells is found in the circulation of melanoma patients and that CEACAM1 serves as immune evasion mechanism from NK and T cells." (PMID 26688824, 2015). "While downregulated in some cancers, CEACAM1 is elevated stepwise during the course of melanoma progression." (PMID 26688824, 2015). "As expected, serum CEACAM1 average levels were significantly (P < 0.001) higher in the whole cohort of melanoma patients as compared with healthy volunteers." (PMID 26688824, 2015). "Based on these findings, we have raised an anti-CEACAM1 blocking antibody that renders melanoma cells more vulnerable to cytotoxic immune cells both in vitro and in vivo and is a promising strategy for treating melanoma patients." (PMID 26688824, 2015). "We have previously shown that CEACAM1 in its soluble form (sCEACAM1) is secreted from several primary cultures and cell lines of human melanoma." (PMID 26688824, 2015). "This is in line with our previous results that serum CEACAM1 correlates with melanoma cell number in culture." (PMID 26688824, 2015). "The concentration of secreted CEACAM1 was found to be proportional to the number of melanoma cells seeded in culture." (PMID 26688824, 2015). "Here we add novel evidences supporting the prognostic role of serum CEACAM1 by using a mice xenograft model of human melanoma and showing a correlation between serum CEACAM1 and tumor burden." (PMID 26688824, 2015). "Another important adhesion molecule, CEACAM-1 (CD66a), was found to be expressed on melanoma cells in 5 out of 6 patients examined." (PMID 24489649, 2014). "CEACAM1 was shown to protect melanoma cells from T cells in vitro, and, moreover, its expression was found on T cells and NK cells from melanoma patients, presumably enabling a homotypic inhibitory interaction." (PMID 24743024, 2014). "Recent reports have shown that the serum CEACAM1 level was increased in pancreatic adenocarcinoma and melanoma patients." (PMID 23885995, 2013). "In contrast, CEACAM1 was also found to be up-regulated in malignant melanoma, thyroid cancer and gastric adenocarcinoma." (PMID 23885995, 2013). "Supporting this immune-inhibitory role, the expression of CEACAM1 on target cells, including melanoma, protects them from being eliminated in vitro by NK and T cells." (PMID 22778766, 2012). "CEACAM1 is considered as an independent, highly significant marker for the development of melanoma metastases and poor survival." (PMID 22778766, 2012). "In searching for localized immune modulators, which act within the tumor milieu and whose manipulation will not lead to severe autoimmunity, we have studied the roles of CEACAM1 in melanoma." (PMID 22778766, 2012). "We have previously demonstrated that serum CEACAM1 (sCEACAM1) is secreted from melanoma cells and correlates with disease progression in metastatic melanoma patients." (PMID 22291846, 2012). "We have recently reported that melanoma cells that have survived an in-vitro T cell attack actively increase CEACAM1 expression in an IFNγ-dependent manner and that this elevation enhances the protective effect against subsequent immune attacks." (PMID 22778766, 2012). "We have recently identified a soluble form of human CEACAM1 (sCEACAM1), which is produced and secreted from melanoma cells in a process that demands active protein synthesis and intact intracellular vesicular transport." (PMID 22291846, 2012). "Membrane-bound CEACAM1 protects melanoma cells from NK and T cells-mediated cytotoxicity and enable them to avoid immune attack." (PMID 22291846, 2012).
melanoma (continued). "Rather, it acts in trans, binding both T cells and melanoma, to efficiently relieve the CEACAM1-dependent inhibition of T cell cytotoxicity." (PMID 22778766, 2012). "In fact, both CEACAM1 and CEACAM5 expressed on melanoma or 721.221 cells suppress NK cell-mediated cytotoxicity against tumor cells by interacting with and activating NK CEACAM1, which is a MHC I-independent inhibitory receptor." (PMID 21731662, 2011). "We selected canine TLM-1 melanoma cells as host for transfection and optimal species-specific expression of canine CEACAM1, -23, -24, -25, -28 and -30, all belonging to the canine CEACAM1 family." (PMID 21436956, 2011). "It was first identified in MHC-I-negative melanoma cells (1106mel) that expression of CEACAM1 blocked the killing by CD16-CEACAM1+ NK cells." (PMID 21731662, 2011). "The highly metastatic cell line UISO-Mel6 broadly confirmed that CEACAM1 is a marker of metastasis in the human melanoma scid mouse model as well." (PMID 17262079, 2007). "Furthermore, CEACAM1 on melanoma cells was previously demonstrated to interact with CEACAM1 on NK‐cells, which in turn upregulates CEACAM1 in the diseased patient." (PMID 41078003, 2025). "CEACAM1 is a transmembrane glycoprotein, which can be expressed on melanoma and immune cells." (PMID 41078003, 2025). "We now show that CEACAM1 is largely restricted from being expressed on monocytic cells or DCs under homeostatic conditions, but neo-expressed on both types of cells in the setting of melanoma." (PMID 38956268, 2024). "In summary, we used a highly specific antibody coupled with an unbiased set of detection platforms enabled by mass cytometry to parse out CEACAM1 expression in fine detail on human immune cells in healthy donor controls and melanoma and in relation to other immune checkpoint markers." (PMID 38956268, 2024). "In addition, soluble CEACAM1 level in sera from melanoma patients inversely correlates with overall survival." (PMID 30871206, 2019). "Interestingly, early in tumor establishment (stage I/II), CEACAM1-4L and CEACAM1-4S were solely expressed, whereas CEACAM1-3L was predominantly and CEACAM1-3S exclusively expressed in progressed melanoma (III/IV)." (PMID 30871206, 2019). "Analyses of a large cohort of melanoma cell lines revealed a CEACAM1 expression rate of 72%." (PMID 30871206, 2019). "This has spurred discussion of CEACAM1 as a more specific and sensitive biomarker than the currently used Melan-A, S100β and HMB45, and has implicated CEACAM1 as a potential novel therapeutic target in melanoma." (PMID 30871206, 2019). "However, as the cell line used in this study is BRAF wildtype it is still possible that CEACAM1 signaling affects IGFBP7 expression in certain subsets of patients (e.g. patients with BRAF wildtype melanoma)." (PMID 30089785, 2018). "High percentages of circulating NK and CD8+ lymphocytes are CEACAM1+ in melanoma patients." (PMID 30406153, 2018). "The overwhelming evidence of CEACAM1 importance in melanoma solidify the claim that this adhesion molecule could be applied as an improved prognostic and predictive biomarker for melanoma patients over the commonly used Breslow depth." (PMID 30406153, 2018). "LXN expression could be investigated by immunohistochemistry in melanoma from 105 patients of the same cohort from which the results for CEACAM1 expression were obtained." (PMID 30089785, 2018). "In selected tumor types like melanoma and glioma, first experiments indicate that CEACAM1 might be a suitable target for immunotherapy." (PMID 30050594, 2018). "According to the data presented here this could probably be achieved by blocking CEACAM1 in some melanoma subsets (e.g. BRAF wildtype with high CEACAM1 expression)." (PMID 30089785, 2018).